CD4 (CD4 molecule)
Diseases named in the same sentence as CD4 in open-access papers (continued):
Sharing a sentence is not in itself a finding about the gene and the disease.
Allergy (continued). "Memory CD4+ T cells, including Th2 effector cells, are key components in the pathogenesis of allergic diseases and helminth infections." (PMID 38587077, 2024). "In the initiation of the respiratory allergic reactions, the allergen-specific CD4+ Th2 lymphocytes typically play a key role by stimulating the production of specific IgE antibodies directed at the allergens." (PMID 39201554, 2024). "By acting on DCs and promoting the expression of OX40 ligand (OX40L), CD80, and CD86, TSLP promotes allergic reactions by stimulating the differentiation of naive CD4+ T cells into pro-inflammatory TH2 cells that generate IL-4, IL-5, IL-13, and TNF." (PMID 39057040, 2024). "Regarding the broad allergic disease (BAD), CD4+ T cells and monocyte cells had significant causal effects on it (p = 3.90 × 10–4 and p = 2.46 × 10–3)." (PMID 38263182, 2024). "The intestinal immune system must tolerate food antigens to avoid allergy, a process requiring CD4+ T cells." (PMID 37191720, 2023). "In the case of allergy, Il-6 and IL-1β have been shown to break allergen-specific CD4+ T cell tolerance." (PMID 36756279, 2023). "They observed that children who outgrew their allergy, had higher frequencies of circulating CD4+CD25+ Treg cells after in vivo milk exposure and that these cells suppressed the effector T cell function." (PMID 36756279, 2023). "In patients with allergy to metals, the level of iOPN CD4 T cells was statistically higher in the acute stage than in remission (p < 0.05)." (PMID 36835932, 2023). "To gain insight into the polyclonal repertoire dynamics of CD4+ T cell responses to food protein in the context of feeding, tolerance, or allergy, we next assessed TCRs from our scRNAseq dataset." (PMID 37191720, 2023). "Prenatal L. reuteri supplementation was shown to change DNA methylation patterns in CD4+ T cells of newborns enhancing immune activation at birth, resulting in affecting immune maturation and allergy development." (PMID 37520545, 2023). "In both tolerance and allergy, we found altered functional gene expression programs in incoming Tregs, as well as altered transcriptional programs in resident IE CD4+ T cells." (PMID 37191720, 2023). "Dendritic cells play essential roles in allergy sensitization, CD4+ naïve T cell activation, and T cell differentiation." (PMID 37469874, 2023). "C57BL/6 mice do not typically have a strong Th2 response in the CT allergy model and we did not see significant increases in IL-4 production among Tomato+ CD4+ T cells from allergy mice." (PMID 37191720, 2023). "CD4+ regulatory T (Treg) cells are important in promoting immune tolerance to allergens and preventing allergic diseases." (PMID 36831258, 2023). "Dendritic cell activation by TSLP accelerates the development of CD4 naive T cells into T-helper 2 cells by facilitating antigen presentation to CD4 naive T cells during allergic reactions." (PMID 36601189, 2023). "Immunostaining and flow cytometry were carried out to show allergic reactions and the activation of CD4 + T cell subsets in the conjunctiva and cervical lymph nodes (CLNs)." (PMID 37784129, 2023). "Given that the STAT6 axis is critical for the differentiation of TH2 cells, a subset of CD4+ helper T cells that is a major contributor to the pathogenesis of allergic disease, we next investigated TH2 signatures in these patients." (PMID 36884218, 2023). "BLG associated with zinc resulted in lower proliferation of CD4+ and CD8+ T cells and promoted a Th1 cytokine milieu, which ultimately counteracts allergy development." (PMID 35392214, 2022). "TH2-type CD4+ T cells and the cytokines that produce IL-4, IL-5, and IL-13 are considered major players in the pathophysiology of allergic diseases." (PMID 36364962, 2022). "A greater number of CRTH2+ CD4 T cells was observed in patients with allergic diseases and was positively correlated with the severity of allergic airway or gastrointestinal inflammation." (PMID 36591273, 2022).
Allergy (continued). "SST has also been reported to suppress TH2-type allergic reactions, affecting the differentiation of naive CD4+ T cells to Th1 or TH2 cells." (PMID 36297517, 2022). "Altogether, OX40L derived from immune cells, including DCs and mast cells, is crucial for the development, maintenance, and reactivation of allergen-specific memory CD4 T cells to exacerbate allergic diseases." (PMID 36591273, 2022). "TLRs promote the differentiation of naive CD4+T cells to T helper (Th) cells, activate the immune response, and participate in the pathogenesis of autoimmune and allergic diseases." (PMID 35514979, 2022). "Although memory T cells are generally believed to be formed in response to acute infections, the pathogenesis and persistence of chronic inflammatory diseases, including allergic diseases, are also related to the effector functions of memory CD4 T cells." (PMID 36591273, 2022). "Altogether, these results imply that tissue-derived cytokines have many aspects to reactivate allergen-specific memory CD4 T cells for the pathology of allergic diseases." (PMID 36591273, 2022). "In the course of urushiol-induced allergy, mitochondrial antigens can undergo degradation by the mitophagy induced after organelle damage, resulting in class II presentation to CD4+ T cells." (PMID 34711292, 2021). "Data in the literature showed that during eosinophilic and neutrophilic inflammations from CR-allergy, 30 and 10%, respectively, of the CD4+ T cells that infiltrated into lungs were FoxP3+, which is one of the signatures of potent immune suppression." (PMID 34135902, 2021). "Using this laboratory mouse allergy model and a newly developed peptide pool of mouse allergens, we studied CD4 T cell responses with the aim to characterize this regulatory process and explore its underlying mechanisms." (PMID 33616085, 2021). "In this paper, we set out to assess the epigenome-wide effects of combined maternal probiotic and ω-3 intervention during the latter half of pregnancy on CD4+ cells from cord blood samples in an on-going allergy prevention trial." (PMID 34193262, 2021). "IFN‐γ inhibits the collection of eosinophils by inhibiting CD4+ T cell infiltration, reducing IL‐4 and IL‐5 production, inhibiting the synthesis of IgE, and attenuating allergy‐induced airway inflammation." (PMID 33421348, 2021). "None of the studies made conclusive observations on major differences in the activation or role of CD4+ and CD8+ T cell subsets in chemical-associated allergies." (PMID 35011644, 2021). "The data illustrate that CD8+ Tregs are activated in allergic state and perform their functions in the suppression of local inflammation in allergic diseases, just as CD4+ Tregs do." (PMID 34294130, 2021). "Our previous studies have shown that soluble peptides based on CD4+ T cell epitopes can protect from autoimmune and allergic diseases." (PMID 33936079, 2021). "Our results suggest that MQL is a potential therapeutic agent for CD4+ T cell-mediated diseases, including allergic diseases." (PMID 34356353, 2021). "More recently, the novel subset of CD4+ T-cells (Tfh cells), which was introduced into allergic diseases and AIT, plays a crucial role in the production of IgE and contributes to the class switching of antibodies." (PMID 34804031, 2021). "The CD4+ T cell-mediated cellular response plays a crucial role in an allergic reaction, which involves lymphocyte activation and cytokine production." (PMID 34207474, 2021). "In typical murine allergy models, production of antigen-specific CD4+ T cells is induced in normal mice by the systemic administration of an antigen with an adjuvant." (PMID 33050549, 2020). "Using CD4+ T cell-depleting procedure, the essential contribution of CD4+ T cells were also demonstrated by other researchers and in other allergy models." (PMID 33050549, 2020).
Allergy (continued). "Previous reports show that CD4+ T cells from patients with allergic diseases express high levels of Bcl2L12 16, 17, the present data also show that sTh2 cells express high Bcl2L12 levels." (PMID 31929750, 2020). "Activation and differentiation of T cells exerts a critical role in the allergic disease, and CD4+T cells differentiate into Th1 cells and Th2 cells." (PMID 32765268, 2020). "Antigen-specific CD4+ T cell-cloned mice are expected to be useful for investigating the detailed role of CD4+ T cells in various allergic diseases and for evaluating novel anti-allergic drugs." (PMID 33050549, 2020). "Numerous evidences indicating the importance of CD4+ T cells and T cell cytokines for the development of inflammatory responses in allergic diseases were accumulated in the early 1990s." (PMID 33050549, 2020). "Recently, CD4+ T cell-dependent allergic inflammation models are widely used and applied for investigating allergic diseases not only in the respiratory tract but also in other target organs, such as nasal mucosa, skin, and the digestive tract." (PMID 33050549, 2020). "IL-4Rα signaling on Tregs modulates expansion and the functional stability of CD4+CD25+FoxP3+ Tregs in vivo during allergic disease." (PMID 32931477, 2020). "These new models of CD4+ T cell-mediated allergic inflammation using the cloned mice exert their full potential for elucidating the pathogenesis of allergic diseases and evaluating the efficacy and/or screening of anti-allergic drugs." (PMID 33050549, 2020). "Allergic rhinitis (AR) is a common allergic disease which is characterized by the promotion of Th2 differentiation of CD4+ T cells." (PMID 32242002, 2020). "Although CD4 Th2 cells are commonly involved in parasitic responses and allergy, their role in pancreatic cancer seems to be the exacerbation of fibrosis and prevention of collagen clearance." (PMID 31796877, 2019). "NIP45, a transcription factor regulating NFATc1 activity, mRNA was found to be induced in the Peripheral Blood mononuclear cells (PMBCs) of asthmatic pre-school children with allergies and in the peripheral blood CD4+ T cells from adult asthmatic patients." (PMID 31666531, 2019). "While IL-17-associated genes identified in lung are detected in blood, the allergy signature is only detectable in blood CD4+ effector cells." (PMID 31253760, 2019). "IgE has been considered a biomarker of many allergic diseases, and IgE production is dependent on CD4+ T cells." (PMID 30824845, 2019). "LTT can be positive in a patient with a metal allergy unrelated to an implant, while an elevated CD4/CD8 ratio however is more specific for an inflammatory reaction occurring in the joint synovium." (PMID 30109436, 2018). "The primary reasons for premature discontinuation of CPT were CD4 greater than 350 cells/mm3, severe sulfa allergy and first trimester of pregnancy." (PMID 30042677, 2018). "Eosinophils are multifunctional cells that have cytotoxic proinflammatory activities and stimulate CD4+ T-cells in experimental models of allergy and parasitic infections." (PMID 29445372, 2018). "Collagen‐peptide ingestion suppresses allergic responses by skewing the balance of CD4+ T cells toward Th1 and Treg cells and seems to be a promising agent for preventing allergies and inflammatory diseases." (PMID 29388365, 2018). "Shrimp allergy is known to be mediated through the IgE mechanism, with the recognition by naïve CD4 + T cells of antigenic tropomyosin peptides presented by HLA class II molecules known to be the trigger for the IgE mediated hypersensitivity reaction." (PMID 29348432, 2018). "Consistent with this, IL-7R blockade in a Th2 allergy model led to decreased numbers of airway resident CD4 T cells." (PMID 30386342, 2018). "In allergic diseases, the balance among the subsets of effector CD4+ T cells and regulatory T (Treg) cells plays a crucial role in controlling pathological conditions." (PMID 29388365, 2018).
Allergy (continued). "The inhibition of allergic reactions is accompanied by increased numbers of CD4 (+) Foxp3 (+) T cells." (PMID 30459600, 2018). "Cellular therapies with CD4+ T regulatory cells (Tregs) hold promise of efficacious treatment for the variety of autoimmune and allergic diseases as well as posttransplant complications." (PMID 29379498, 2017). "This parallels previous estimates of locus contribution to CD4 T cell responses in allergy and Mtb, which suggest predominant restriction by the DR loci, with lesser, but appreciable contributions by DQ and DP." (PMID 27409590, 2016). "(ii) In the allergy propagation phase, re-exposure to ingested food antigens activates emigrated antigen-specific CD4+TH2 memory/effector cells in the small intestine to produce IL-13, resulting in the increase of intestinal IL-25 production." (PMID 27853507, 2016). "Children who developed allergies in the first 3 years of life had lower numbers of CD4+CD25+FOXP3+ T cells and reduced FOXP3 expression and IL-10 production as newborns (P < 0.05)." (PMID 27646403, 2016). "We observed an increase in CD4+ CD45RA+ cells 2 weeks from the beginning of allergy season in comparison with the onset of symptoms." (PMID 27799958, 2016). "This study investigated the effect of DEX in CE-induced allergic reactions, especially the role of CD4 + CD25 + FOXP3+ Treg cells and some cytokines." (PMID 26968945, 2016). "Ingested probiotics are recognized by pattern recognition receptors, such as TLRs on DCs, that are essential for immunological homeostasis in the gut and that play an important role in allergic diseases; therefore, CD4+Foxp3+ Tregs are increased in MLNs." (PMID 27802847, 2016). "IL5 is directly involved in eosinophil activation and is a key molecule in allergy and eosinophilic inflammation, expressed by CD4+ helper T and B cells, mast cells, and eosinophils." (PMID 26693492, 2015). "A characteristic feature of allergic diseases is the appearance of a subset of CD4+ cells known as TH2 cells, which is controlled by transcriptional and epigenetic mechanisms." (PMID 26459392, 2015). "As a new member of CD4+ T cell family, Th9 cells have been known to play a significant role in some diseases, such as allergic diseases and cancers as well as the parasitic infections." (PMID 26509179, 2015). "We then describe the results of our gene expression profiling of immune cells key to allergy (CD4+ lymphocytes), collected from the peripheral blood of selected subjects who had undergone GWAS (blue box)." (PMID 25085501, 2014). "Our results showed that patients with severely reduced CD4 cell counts continued to suffer from symptoms of IgE-mediated allergy and produced allergen-specific IgE antibodies." (PMID 24896832, 2014). "Levels of CD4+ IFN-γ+ (Th1), IL-13+ (allergy-associated Th2), as well as IL-17+ and IL-10+ (immunoregulatory) cells peaked at 72 hours in mice exposed to WT conidia and indicated a mixed Th1, Th2 and Th17 response." (PMID 25340353, 2014). "They report similar roles for CD8+ and CD4+ cells via the production of cytokines, such as IL-4, or other inflammatory mediators, which is typical of allergic disease." (PMID 25050125, 2014). "The IL-5 gene is expressed in CD4+ T-cells, masT-cells, and eosinophils, and in allergic reactions the expression level of the IL-5 gene can be varied." (PMID 24764725, 2014). "Th2 cells contribute to responses to parasites and many allergic diseases, but they represent a small fraction of CD4+ effectors during respiratory viral infections." (PMID 25051576, 2014). "Our results extend these results to an in vitro human cell model of allergen response showing that complement system plays a role in allergy probably by regulating differentiation of CD4+ T cell towards Th2 subtype or by modulating T cell activation." (PMID 24116013, 2013).
Allergy (continued). "The expression of GSDMB in the thymus and CD8+ and CD4+ T-cells would increase the plausibility of this inference, especially given the involvement of type 1 and type 2 immune responses in autoimmune and allergic disease respectively." (PMID 24044605, 2013). "Th2 T cells: CD4+ T cells that express T-helper 2 (Th2)-type cytokines, such as interleukin (IL)-4, IL-5 and IL-13, and mediate immune responses in allergic diseases and parasitic infections." (PMID 23828644, 2013). "As for other conditions (e.g., allergic reactions) mechanisms driving the change in phenotype of allergen-specific CD4+ T cell effectors following immunotherapy remain to be determined." (PMID 23966946, 2013). "In a separate model, eosinophilia was associated with having any positive parasitic infection or serologic test when controlling for CD4+ cell count and seasonal allergies (OR = 3.0; 95% CI: 1.2–7.4)." (PMID 21532747, 2011). "While the role of CD4+ T cells in the pathogenesis of allergic disease is well established, that of CD8+ T cells is less well defined." (PMID 15783262, 2005). "However, our study showed that allergen-specific Tregs with regulatory activity can be obtained from naïve CD4+ T cells from the intestinal immune system of mice even with severe allergy." (PMID 40446078, 2025). "Previous studies have reported that peripheral blood mononuclear cells (PBMCs) from patients with active cow’s milk allergy had considerably stronger proliferative activity against β-lactoglobulin after milk challenge than outgrown allergy patients with higher circulating CD4+CD25+ Tregs." (PMID 39729447, 2024). "Tfh cells are a subset of CD4+ T cells that reside in the germinal center of lymph nodes and are essential to produce high-affinity antigen-specific IgE and subsequent IgE-mediated allergic reactions." (PMID 38254689, 2024). "To further elucidate the nature of these cells, we performed a comprehensive phenotypic and transcriptional analysis at single-cell resolution to interrogate the CD4+ T cell diversity and their contribution to immune regulation in helminth infection and/or allergic diseases." (PMID 38587077, 2024). "We also investigated CD4+ T helper cells in OVA-induced allergy response." (PMID 36980282, 2023). "Our team previously developed a new approach investigating CD4+ T cell proliferation in PBMCs and food‐specific IgG4 in esophageal biopsies, which had higher success identifying trigger foods compared to previous reports with allergy tests." (PMID 37773691, 2023). "Furthermore, the protein-lipid complexes supressed CD3+ CD4+ cell numbers which indicates an immunosuppressive effect on this population, which is pivotal in allergy induction." (PMID 35495627, 2022). "Consistent with observations in the mouse model, human cord blood CD4+ T-cells from hypercholesterolemic mothers showed enhanced mRNA expression of TH2 cytokines, which was associated with an increased risk of developing allergic diseases later in life." (PMID 35745240, 2022). "However, recent investigations have discovered regulatory T (Tregs) cells as an additional crucial subset of CD4+ T cells, which is essential in mediating allergic disease." (PMID 36601108, 2022). "Therefore, CD4+ T cells play a dominant role in the type I immune response of these two allergic diseases, the mechanism of which appears to be an interesting topic." (PMID 36713372, 2022). "Current research suggested that it may contribute to a variety of cytological processes of T cells in different allergic diseases, including Treg deficiency, TH1 and TH2 polarization, and differentiation of CD4+ T cells." (PMID 36713372, 2022). "Here, we review the characteristics of allergen-specific memory CD4 T cells in allergic diseases and the importance of extrinsic factors for the homeostasis and reactivation of these T cells in the view of mediating persistence, recurrence, and aggravation of allergic diseases." (PMID 36591273, 2022).